SON (SON DNA and RNA binding protein)
Description:
RNA-binding protein that acts as a mRNA splicing cofactor by promoting efficient splicing of transcripts that possess weak splice sites. Specifically promotes splicing of many cell-cycle and DNA-repair transcripts that possess weak splice sites, such as TUBG1, KATNB1, TUBGCP2, AURKB, PCNT, AKT1, RAD23A, and FANCG. Probably acts by facilitating the interaction between Serine/arginine-rich proteins such as SRSF2 and the RNA polymerase II. Also binds to DNA; binds to the consensus DNA sequence: 5'-GA[GT]AN[CG][AG]CC-3'. May indirectly repress hepatitis B virus (HBV) core promoter activity and transcription of HBV genes and production of HBV virions. Essential for correct RNA splicing of multiple genes critical for brain development, neuronal migration and metabolism, including TUBG1, FLNA, PNKP, WDR62, PSMD3, PCK2, PFKL, IDH2, and ACY1.
Synonyms: BASS1; C21orf50; KIAA1019; NREBP; DBP-5; FLJ21099; FLJ33914; SON3; TOKIMS
Tractability: PROTAC: UniProt records ubiquitination sites on it; ubiquitination databases record sites on it; its protein half-life has been measured.
Gene: Protein-coding gene on chromosome 21 (33,543,038 to 33,577,481, forward strand). Ensembl gene ENSG00000159140.
Subcellular location: Nucleus speckle
Subcellular location (Human Protein Atlas): Nuclear speckles
Gene Ontology:
Molecular function: protein binding; RNA binding; nucleic acid binding; RS domain binding
Biological process: microtubule cytoskeleton organization; mitotic cytokinesis; mRNA processing; negative regulation of apoptotic process; regulation of cell cycle; regulation of mRNA splicing, via spliceosome; regulation of RNA splicing
Cellular component: nuclear speck
Genetic constraint (gnomAD): Loss-of-function variants: 3 observed, 151.77 expected, observed/expected ratio (o/e) 0.0198, 90% interval 0.008 to 0.051. The upper end of that interval is the gene's LOEUF score, 0.051, which puts it in group 1 of 6, group 1 being the genes least tolerant of losing a copy. Missense variants: 2,576 observed, 2,962.8 expected, observed/expected ratio (o/e) 0.87, 90% interval 0.84 to 0.9. Synonymous variants: 1,143 observed, 1,080.7 expected, observed/expected ratio (o/e) 1.06, 90% interval 1.01 to 1.11.
Gene-disease validity (ClinGen):
ClinGen rates the evidence that SON causes each of these diseases.
ZTTK syndrome (autosomal dominant): Definitive.
Homologues: Orthologues: chimpanzee SON (99% identical), macaque SON (93% identical), pig SON (90% identical), rat Son (87% identical), mouse Son (86% identical), rabbit SON (86% identical), dog SON (83% identical), guinea pig SON (82% identical), zebrafish sona (12% identical), Caenorhabditis elegans D1037.1 (10% identical), Drosophila melanogaster Son (10% identical).
Diseases named in the same sentence as SON in open-access papers:
SON is named in the same sentence as 54 diseases in open-access papers, as found by Europe PMC text mining. Sharing a sentence is not in itself a finding about the gene and the disease. The quoted sentences say what the papers report.
ZTTK syndrome (11 papers, 2020 to 2025). "Zhu-Tokita-Takenouchi-Kim syndrome (ZTTK syndrome) is a severe multi-systemic developmental disorder, caused by variants in the SON gene." (PMID 38566089, 2024). "Thereby, ZTTK syndrome was named after the first authors who correlated the phenotypic findings with the pathogenic mutation in the SON gene." (PMID 37476413, 2023). "Gene SON is associated with ZTTK syndrome (#617140), which is a severe multisystem developmental disorder and has congenital defects of the heart in some patients." (PMID 35910219, 2022). "The paper discusses two unrelated Polish patients with ZTTK syndrome in whom de novo heterozygous truncating variants in exon 3 of the SON gene were found." (PMID 32705777, 2020). "Among the 31 de novo mutations in the SON gene reported to be associated with ZTTK syndrome so far, twenty-eight encode truncated SON proteins due to either frameshift or nonsense substitutions that generate premature termination codons." (PMID 32448361, 2020). "Rescue experiments that involved the introduction of two forms of disease-associated mutant SON proteins confirmed that the truncated SON proteins encoded by mutant SON genes differ in their residual functions, even though both mutations cause ZTTK syndrome." (PMID 32448361, 2020). "Rescue experiments that induced the expression of human wild-type SON protein and truncated SON proteins encoded by disease-associated mutant SON genes provided further information relevant to the pathophysiology of ZTTK syndrome." (PMID 32448361, 2020). "There are 33 cases of ZTTK syndrome reported to date worldwide (except the present case), and 26 causative SON variants have been identified so far." (PMID 32926520, 2020). "It is, therefore, not surprising that hSONm2 encoded by the most prevalent mutant SON associated with ZTTK syndrome retained considerable function in neural development." (PMID 32448361, 2020). "We report here a young child affected by ZTTK syndrome with SON mutations." (PMID 36540882, 2022). "In addition, a truncated form of SON encoded by the most prevalent mutant SON identified in ZTTK syndrome patients can ameliorate the neuronal abnormalities induced by Son knockdown." (PMID 32448361, 2020). "Given recent discoveries on the pathogenic effects of compromised SON function in ZTTK syndrome, as well as the diverse cellular functions of SON in RNA splicing, transcription, and nuclear speckle organization, there is a pressing need for appropriate model organisms with disrupted SON expression." (PMID 38290089, 2024). "However, the functional significance of SON in neural development is largely unknown, and the pathological consequence of SON haploinsufficiency underlying the neural phenotypes of ZTTK syndrome, such as ID and brain malformation, remains undetermined." (PMID 32448361, 2020). "In 2/61 cases, RNA-seq revised diagnoses (EPG5 to LZTR1 in an individual with a Noonan syndrome-like disorder) and discovered an additional relevant gene (CEP120 in addition to SON in an individual with ZTTK syndrome)." (PMID 40593860, 2025). "SON haploinsufficient mice serve as an animal model of Zhu-Tokita-Takenouchi-Kim syndrome and identify indispensable SON functions in multi-organ development and hematopoiesis." (PMID 38290089, 2024). "To verify that the hematopoietic features found in ZTTK syndrome are due to SON LoF, we further analyzed the hematopoiesis of our Son+/– mice." (PMID 38290089, 2024). "Our report expands the mutant spectrum of SON gene and refine the genotype‐phenotype map of ZTTK syndrome." (PMID 32926520, 2020). "Our report expands the mutant spectrum of the SON gene and refines the genotype‐phenotype map of ZTTK syndrome." (PMID 32926520, 2020). "In patients with ZTTK syndrome, SON haploinsufficiency leads to the disturbances of multi‐organ development and thus to multi‐organ defects." (PMID 32705777, 2020).
ZTTK syndrome (continued). "The pathophysiological consequence of SON insufficiency in brain development is therefore of great interest to understand the neural symptoms of ZTTK syndrome." (PMID 32448361, 2020). "Further investigations on terminal differentiation processes of each lineage and the origin of lineage bias will enable us to understand more about SON’s role in different hematopoietic lineages and how SON haploinsufficiency alters hematopoiesis in ZTTK syndrome." (PMID 38290089, 2024). "This aligns with the absence of identified patients with ZTTK syndrome with homozygous SON loss-of-function mutations." (PMID 38290089, 2024). "Here, we report the first case of ZTTK syndrome in Latin America, a 3-year-old boy with a de novo non-sense mutation in the SON gene, never reported in the literature." (PMID 37476413, 2023). "It is suggested that ZTTK syndrome is caused by SON haploinsufficiency; potentially functional proteins encoded by mutant SONs are not involved in pathogenesis of ZTTK syndrome due to NMD." (PMID 32448361, 2020). "In addition, rescue experiments provided further evidence supporting that putative neural abnormalities in ZTTK syndrome are caused by SON haploinsufficiency regardless of the residual functions of mutant SON genes." (PMID 32448361, 2020). "We also applied truncated SON proteins encoded by disease-associated mutant SON genes for rescue experiments and found that a truncated SON protein encoded by the most prevalent SON mutant found in ZTTK syndrome rescued the neural abnormalities while another much shorter mutant SON protein did not." (PMID 32448361, 2020). "In addition, the results support that the neural abnormalities in ZTTK syndrome are caused by SON haploinsufficiency independent of the types of mutation that results in functional or dysfunctional proteins." (PMID 32448361, 2020). "In addition, this data supports the idea that the neural abnormalities in ZTTK syndrome are caused by SON haploinsufficiency rather than functional or dysfunctional proteins resulting from different types of mutations." (PMID 32926520, 2020).
Intellectual disability (7 papers, 2020 to 2025). "SON encodes a DNA binding protein in which de novo truncating variants have been shown to cause intellectual disability and congenital malformations, the likely diagnosis for this case." (PMID 38540401, 2024). "De novo mutations in SON have been linked to intellectual disability, and gene expression studies suggest that it is a master regulator of genes involved in neurodevelopment." (PMID 32066674, 2020). "Zhu‐Tokita‐Takenouchi‐Kim syndrome caused by SON mutation is characterized by congenital hypotonia and developmental delay as well as intellectual disability with behavioral problems." (PMID 32705777, 2020). "SON is a DNA and RNA binding protein, and its mutations cause Zttk (Zhu–Tokita–Takenouchi–Kim) syndrome, another severe multisystem developmental disorder characterized by intellectual disability and psychomotor development." (PMID 39299805, 2024). "Zhu-Tokita-Takenouchi-Kim (ZTTK) syndrome, a rare congenital anomaly syndrome characterized by intellectual disability, brain malformation, facial dysmorphism, musculoskeletal abnormalities, and some visceral malformations is caused by de novo heterozygous mutations of the SON gene." (PMID 32448361, 2020). "Moreover, as mutations in SON may also explain a part of cases of apparently isolated intellectual disability, we suggest to include SON into the clinical panel of genes associated with developmental and intellectual disability, testing by the NGS method." (PMID 32705777, 2020).
leukemia (4 papers, 2018 to 2021). A malignant (clonal) hematologic disorder, involving hematopoietic stem cells and characterized by the presence of primitive or atypical myeloid or lymphoid cells in the bone marrow and the blood. "SON was also described as a negative regulatory element binding protein (NREBP) due to its transcriptional repression of human hepatitis B virus genes and regulates the transcriptional initiation of leukemia-associated genes in human and mouse cells." (PMID 33630943, 2021). "Additionally, SON is an RNA splicing factor that plays a role in the transcription of leukemia-associated genes." (PMID 33630943, 2021). "In human, mutations in SON have been linked to brain developmental defects and leukemia." (PMID 31730657, 2019). "Human SON is located on human chromosome 21 and triplicated in Down syndrome, and these patients have elevated rates of AMKL, TMD, and other leukemias primarily caused by defects in the differentiation of HSPCs." (PMID 33630943, 2021). "Unlike leukemia where we reported that the short isoforms of SON (SON E and SON B) accounts for most of the upregulated SON27, we found that full-length SON (SON F) and its short isoforms are similarly upregulated in brain tumors." (PMID 34548489, 2021).
colorectal cancer (3 papers, 2020 to 2021). A primary or metastatic malignant neoplasm that affects the colon or rectum. "In addition, FAM83H localized to nuclear speckles and interacted with SON, a protein in nuclear speckle, and FAM83H is involved in nuclear recruitment of casein kinase 1α in colorectal cancer cells." (PMID 32460791, 2020).
virus infection (3 papers, 2014 to 2024). "As the occurrence of cardiovascular events during COVID-19 suggests that targeting the endothelium is part of the viral infection course, we surmise COVID-19 patients who have a pre-existing genetic propensity for low SON, OGT, and RORA expression may therefore be more susceptible to cardiac damage." (PMID 33240937, 2020). "SON is involved in pathways regulating virus infection like influenza virus infection as its deletion can lead to reduced influenza viral RNA levels and decreased viral infection suggesting that SON is needed for influenza virus replication." (PMID 33240937, 2020). "In addition, a HTS RNAi study using pandemic swine-origin influenza virus identified 168 factors that inhibit virus infection, including the SON DNA binding protein (SON) that controls the trafficking of virions to late endosomes, as well as CDC-like kinase 1 (CLK1)." (PMID 24952721, 2014).
brain malformation (2 papers, 2020 to 2022). "Data here presented showed that genetic analysis for SON mutations should be suggested in patients with craniofacial anomalies, DD/ID, and cerebral malformations including CM and hydrocephalus." (PMID 36540882, 2022).
Down syndrome (2 papers, 2021 to 2023). "The gene SON is on human chromosome 21 (21q22.11) and is thought to be associated with hematopoietic disorders that accompany Down syndrome." (PMID 33630943, 2021). "Our gene of interest, SON, is located on human chromosome 21 and may play a role in regulation of gene expression associated with the Down syndrome phenotype." (PMID 33630943, 2021).
glioblastoma (2 papers, 2021 to 2022). The most malignant astrocytic tumor (WHO grade IV). "Recent study featured sophisticated interplay of Ptbp1, Ptbp2, RbFox2, and SON (SON DNA and RNA binding protein) promoting glioblastoma multiforme (GBM) genesis." (PMID 35204777, 2022). "Here, we identify SON as a master regulator that activates PTBP1-mediated oncogenic splicing while suppressing RBFOX2-mediated non-oncogenic neuronal splicing in glioblastoma multiforme (GBM)." (PMID 34548489, 2021). "Taken together, these findings demonstrate that SON overexpression in malignant gliomas, especially in GBM, has strong correlations with PTBP1 overexpression and PTBP2 downregulation, suggesting that there is a functional connectivity between SON, PTBP1, and PTBP2 in glioblastoma cells." (PMID 34548489, 2021).
myeloid leukemia (2 papers, 2013 to 2025). A clonal proliferation of myeloid cells and their precursors in the bone marrow, peripheral blood, and spleen. "For example, increased expression of BACH1 (transcriptional regulator of megakaryocytic differentiation process) and SON (homologous sequence with MYC family of oncoproteins) were reported in association with myeloid leukemia in DS." (PMID 23343470, 2013).
absence seizures (1 paper, 2025). "Four genes-HESX1, NCKAP1, SON, STARD9-had not been previously associated with absence seizures." (PMID 41137852, 2025).
anaplastic astrocytoma (1 paper, 2021). "We performed reverse transcription and quantitative PCR (RT-qPCR) using several different primer sets to measure SON and its isoform expression levels in our patient cohort of malignant brain tumors including anaplastic oligodendroglioma, anaplastic astrocytoma and GBM." (PMID 34548489, 2021).
autism (1 paper, 2023). Persistent deficits in social interaction and communication and interaction as well as a markedly restricted repertoire of activity and interest as well as repetitive patterns of behavior. "Examples of these genes include CHD7, ANKRD11, and SON which are robustly associated with both autism and severe developmental disorders." (PMID 36702863, 2023).
bladder cancer (1 paper, 2021). "Moreover, increasing the expressions of NCF2, ETFDH, and SON genes are positively correlated with the incidence of death from bladder cancer." (PMID 34589136, 2021).
brain tumors (1 paper, 2021). "Together, these data reveal significant upregulation of SON in malignant brain tumors and the potential role of SON overexpression in disease progression." (PMID 34548489, 2021). "Interestingly, SON transcripts are significantly upregulated in brain tumors compared to normal brain samples with the highest level observed in GBM patients." (PMID 34548489, 2021). "Importantly, Kaplan–Meier survival analysis obtained from the GlioVis Data Portal demonstrated that high levels of SON expression correlate with short survival of brain tumor patients." (PMID 34548489, 2021). "We therefore examined whether SON expression is altered in brain tumors." (PMID 34548489, 2021). "Collectively, our study reveals that SON-mediated RNA splicing is a GBM vulnerability, implicating SON as a potential therapeutic target in brain tumors." (PMID 34548489, 2021). "Here, we show that SON is aberrantly upregulated in malignant brain tumors with the highest expression level in GBM, the most aggressive form of glioma, and there is a strong correlation between SON upregulation and short patient survival." (PMID 34548489, 2021).
cardiomyopathy (1 paper, 2024). A disease of the heart muscle or myocardium proper. "The identified SON mutation, which plays a crucial role in heart development and mitochondrial function, may be associated with an increased susceptibility to myocardial injury or cardiomyopathy." (PMID 38566089, 2024).
colon cancer (1 paper, 2022). "We first identified SON as a high-risk gene with low expression in colon cancer tissues." (PMID 35991564, 2022). "ALPL, APOL6, SON, VWF, FITM2, and ZEB1-AS1 were significantly differentially expressed in normal and colon cancer tissues." (PMID 35991564, 2022).
epilepsy (1 paper, 2026). A brain disorder characterized by episodes of abnormally increased neuronal discharge resulting in transient episodes of sensory or motor neurological dysfunction, or psychic dysfunction. "Four genes (APOL4, KMT2C, SON, VDR) overlapped a clinical epilepsy panel, supporting the capacity of WGS to recover clinically relevant loci." (PMID 42192833, 2026).
Hydrocephalus (1 paper, 2022). Hydrocephalus is an active distension of the ventricular system of the brain resulting from inadequate passage of CSF from its point of production within the cerebral ventricles to its point of absorption into the systemic circulation. "CM1 and hydrocephalus may be recorded as clinical neurological manifestations of the SON mutations together with others cerebral and systemic organs anomalies." (PMID 36540882, 2022). "Another case of a patient with a variant of the SON gene, CM1, and hydrocephalus as a similar phenotype was previously reported." (PMID 36540882, 2022).
lung adenocarcinoma (1 paper, 2025). A carcinoma that arises from the lung and is characterized by the presence of malignant glandular epithelial cells. "Co-staining reveals that snaR-A RNA spatially surrounds nuclear bodies marked by SON, and that the convergence of snaR-A and SON signal is significant in multiple cell types, including HEK293T and A549 lung adenocarcinoma cells." (PMID 41290606, 2025).
malignant glioma (1 paper, 2021). A grade III or grade IV glioma arising from the central nervous system. "Here, our study identified that SON is highly expressed in malignant gliomas, especially in GBM, and the high level of SON promotes the removal of detained introns from the PTBP1 transcript, thereby upregulating PTBP1 expression and activating PTBP1-mediated oncogenic splicing program." (PMID 34548489, 2021).
microcephaly (1 paper, 2023). A congenital or acquired developmental disorder in which the circumference of the head is smaller than normal for the person's age and sex. "Additionally, in zebrafish models, haploid deficiency of the SON gene causes alteration in the tail length and body axis, associated with eye malformation and microcephaly." (PMID 37476413, 2023).